FASN (fatty acid synthase)
Diseases named in the same sentence as FASN in open-access papers (continued):
Sharing a sentence is not in itself a finding about the gene and the disease.
cancer (continued). "Human ATP citrate lyase (ACLY) and fatty acid synthase (FASN) are fundamental multi‐enzymatic activity proteins for citrate to be metabolized in cancer cells." (PMID 38425123, 2024). "In some cancer cell lines, based on the host gene homologs, FASN has been found to be fused with estrogen receptor, and its overexpression is a common molecular feature in hormone-sensitive cells, being regulated by both estradiol and progesterone." (PMID 39020289, 2024). "FASN provides the building blocks for cell membrane synthesis and energy storage, which are crucial for cancer cell proliferation and survival." (PMID 39408832, 2024). "The initial excitement generated more than two decades ago by the discovery of drugs targeting fatty acid synthase (FASN)-catalyzed de novo lipogenesis for cancer therapy was short-lived." (PMID 38158755, 2024). "For example, cancer cells typically elevate FASN-dependent lipogenesis to support anabolic metabolism and cell growth." (PMID 39483909, 2024). "Pharmacological FASN inhibition is an anti-cancer strategy that can drive NADPH accumulation in cancer cells, promoting ROS signaling and cell death via NOX activity." (PMID 39483909, 2024). "According to several studies, in 35 different cancers, the higher the level of FASN expression, the less the infiltration of immune cells with antitumor function in the TME." (PMID 38272906, 2024). "A wealth of evidence indicates that FASN contributes to the malignant phenotype by inducing the synthesis of fatty acids necessary for the plasma membrane production of the cancer cells and lipid-based post-transcriptional protein modifications." (PMID 39064589, 2024). "Considering the pertinent studies from recent years, we have found targeting FASN with EGCG is advantageous to ameliorate the efficacy of anti-cancer therapy." (PMID 38348027, 2024). "The accumulation of FAs produced by hyperactivated FASN is sufficient to transcriptionally silence MCH-II expression, a causal effector in cancer immune evasion." (PMID 39349429, 2024). "In tumors where PD-L1 is reactively induced by IFNγ secreted by ACPs, FASN blockade, which disrupts the maturation of PD-L1 on the surface of cancer cells, can be used to overcome adaptive immune resistance." (PMID 39349429, 2024). "Key enzymes in fatty acid synthesis, such as Fatty Acid Synthase (FASN), Acetyl-CoA Carboxylase (ACC), and ATP Citrate Lyase (ACLY), are upregulated in various cancers and are closely associated with tumor progression." (PMID 39744129, 2024). "The FASN lipogenic activity acquired by cancer cells to evade immune surveillance should be maintained in established tumors to limit CD8+ T lymphocyte infiltration and promote T cell dysfunction." (PMID 39349429, 2024). "FASN is upregulated in many cancers, including the aggressive triple negative breast cancer (TNBC) subtype." (PMID 39678343, 2024). "For example, fatty acid synthase (FASN), a key enzyme in the lipogenesis pathway, is associated with varying outcomes in different cancer types." (PMID 39624081, 2024). "Inhibiting key enzymes involved in lipogenesis, such as FASN, acetyl-CoA carboxylase, and ATP-citrate lyase, has shown promise in limiting cancer cell proliferation and survival." (PMID 39408832, 2024). "Activated the caspase 2-S1P-SREBP1/2 pathway to up-regulate the expression of DHCR7 and FASN in cancer." (PMID 39906741, 2024). "For example, inhibiting FASN can reduce the proliferation and survival of cancer cells, and FASN inhibitors have shown anti-tumor effects in preclinical models." (PMID 39744129, 2024). "FASN uses citrate‐derived manolyl‐Coa to fuel cancer cells with palmitate, which is converted into phospholipids that change cell membrane composition and polarity, then possibly altering the drug intake into the cell." (PMID 38425123, 2024). "Taken together, these results demonstrate that the suppression of FASN allows CATs to kill cancer cells with a significantly higher degree of efficiency." (PMID 39349429, 2024).
cancer (continued). "FASN: FASN is overexpressed in various types of cancers, where it contributes to the increased production of fatty acids." (PMID 38610991, 2024). "ATP citrate lyase (ACLY), acetyl-CoA carboxylase (ACC), and fatty acid synthase (FASN) are the most highly expressed lipogenic enzymes in several forms of cancer." (PMID 38933330, 2024). "FASN inhibitor TVB-2640 is specifically being evaluated in the treatment of HER2-positive cancer in combination with paclitaxel and trastuzumab." (PMID 38730603, 2024). "Due to TC2N expression showed differences between each BC molecular subtype, we further evaluated the possible correlation between TC2N and FASN expression in the four cancer subtypes." (PMID 38167440, 2024). "Pre-clinical studies show significant anti-cancer effects when FASN is inhibited using genetic or pharmacological approaches." (PMID 38732103, 2024). "For instance, SREBP is one of the most crucial transcription factors that contributes to the elevated FASN level in cancer cells." (PMID 38195819, 2024). "Blocking FASN was associated with increased CD36 expression, ensuring the cellular availability of fatty acids to sustain cancer cell proliferation." (PMID 39339236, 2024). "FASN is essential for de novo fatty acid synthesis to support metastatic progression and stemness of human cancers." (PMID 38167440, 2024). "Further, investigation of the combined effects of ALDH and FASN inhibitors, as well as their derivatives, across various cancers is crucial to explore their potential in preventing cancer progression by inhibiting CSC growth and progression." (PMID 39456967, 2024). "In cancer, cells upregulate lipogenic enzymes, including citrate synthase and fatty acid synthase, to meet the increased demand for fatty acids and cholesterol synthesis." (PMID 39795950, 2024). "Cerulenin is a specific FASN inhibitor possessing the capability to suppress malignant phenotypes and induce apoptosis in cancer cells." (PMID 39332525, 2024). "The key enzyme of the fatty acid biosynthesis pathway, fatty acid synthase (FASN), is widely recognized as a promising therapeutic target in cancer and other health conditions." (PMID 38766222, 2024). "The in vitro and in vivo experiments used a drug (TVB3166) for FASN inhibition that showed a reduction in cancer stem cells and tumor growth in both tests." (PMID 39409942, 2024). "Our biomathematical model suggests that suppression of FASN-driven lipogenesis renders cancer cells less efficient in the use of metabolic resources and more susceptible to killing by cytotoxic T lymphocytes." (PMID 39349429, 2024). "Targeted FASN depletion primes cancer cells for mitochondrial apoptosis as it synergizes with BCL-2/BCL-XL-targeting BH3 mimetics to render cancer cells more susceptible to T-cell-mediated killing." (PMID 39349429, 2024). "The relationship between FASN status and prognosis strongly suggests that FASN-catalyzed endogenous adipogenesis provides a growth and survival advantage to cancer cells." (PMID 38408962, 2024). "We detected in PR elevated levels of enzymes (COX-2, ACSS2, FDPS, FASN, ACAT2, ACLY, SLC12A2) and metabolites (arachidonic acid and carnitine) involved in lipid metabolism, which have been linked to radioresistance of cancer cells." (PMID 38410100, 2024). "Cancer cells also upregulate fatty acid synthase, which converts acetyl-CoA to long-chain fatty acids." (PMID 38339256, 2024). "The upregulation of FASN and other lipogenic enzymes is a common feature in cancer cells, supporting their rapid proliferation by providing necessary lipids for membrane synthesis and energy production." (PMID 39408832, 2024). "These intriguing discoveries highlight the potential of targeting FASN PTMs as a therapeutic strategy in cancer." (PMID 39551780, 2024). "The present results showed that FASN expression is significantly higher in PCa than in all other types of cancer in TCGA database, suggesting the unique and critical role of FASN in PCa." (PMID 39309439, 2024).
cancer (continued). "Inhibition of lipogenic enzymes, such as FASN, has been shown to have anti-tumor effects in preclinical models of various cancers." (PMID 38287402, 2024). "Specifically, fatty acid synthase (FASN), the rate-limiting enzyme in the de novo FA synthesis pathway has been widely reported to act as a pro-oncogenic enzyme and promote cancer progression." (PMID 39337514, 2024). "This disruption is crucial due to FASN’s overexpression in cancer cells, which leads to increased lipid synthesis and suppresses TNF-α." (PMID 39329757, 2024). "The FASN gene is the primary focus among adipogenic genes and the antitumor activity of several FASN inhibitors has been demonstrated in preclinical cancer models." (PMID 38994204, 2024). "The upregulation of FASN is commonly observed in cancer cells, contributing to their uncontrolled growth and survival." (PMID 39071712, 2024). "Taken together, these analyses suggest that FASN gene expression is negatively correlated with cancer-suppressing immune landscapes and positively correlated with features of cancer immune escape." (PMID 39349429, 2024). "The downregulation of FASN by CV is an important indicator for its possible anti-cancer activities particularly given its high expression in HCC." (PMID 38992651, 2024). "Fatty acid synthase (FASN), a key enzyme of de novo lipid synthesis, is the most targetable among lipogenesis genes due to its high degree of overexpression in cancer cells as compared to normal epithelial cells." (PMID 38732103, 2024). "We now propose that a basic metabolic program such as FASN-dependent endogenous lipogenesis is a metabolic checkpoint that functions as part of the intrinsic defense mechanisms that cancer cells employ to escape to the stress imposed by infiltrating T cells." (PMID 39349429, 2024). "Fatty acid synthase (FASN) is vital for lipid synthesis and is associated with oncogenic activity in various cancers." (PMID 39169426, 2024). "Analysis of different cancer types revealed that FASN was significantly overexpressed in 11 of 24 tumor types (45.8%)." (PMID 39309439, 2024). "In other cancers, FASN overexpression begins in the precancerous stage and persists through the course of the disease." (PMID 38539424, 2024). "These events likely act in concert to contribute to the anti-cancer effects observed upon FASN inhibition." (PMID 39678343, 2024). "EGFR, phosphatidylinositol 3‐kinase (PI3K)/AKT, and RAS/MAPK signaling pathways are important regulators of metabolism, including lipid metabolism (such as that involving FASN), in cancer." (PMID 38874588, 2024). "The contribution of FASN to tumor initiation, cancer cell growth and survival, therapeutic resistance, and tissue-specific metastasis has received considerable attention over the past two decades." (PMID 39349429, 2024). "Orlistat, another FASN inhibitor, demonstrated cytotoxic effects in various cancer cell lines and xenograft models." (PMID 38610991, 2024). "Accordingly, ACLY (ATP citrate lyase) and FASN (fatty acid synthetase) which are involved in de novo fatty acid synthesis are both greatly upregulated in cancer cells." (PMID 38402237, 2024). "Research has demonstrated that apoptosis is induced when FASN is blocked in cancer cells, and cell growth arrest occurs." (PMID 39273552, 2024). "Elevated FASN expression is frequently observed in multiple cancers and has been demonstrated to promote cancer cell proliferation, survival and metastasis, which results in a higher risk of disease-related death." (PMID 38195819, 2024). "O-GlcNAcylation of FASN enhances its activity, thus protecting cancer cells from starvation, and dual inhibition of O-GlcNAcylation and FASN synergistically induces cancer cell death." (PMID 39178944, 2024). "Most healthy cells preferentially use the lipids provided by the diet for the normal production of new structural lipids, whereas cancer cells favor their de novo endogenous synthesis through the overexpression of FASN." (PMID 38611595, 2024).
cancer (continued). "FASN is often upregulated in cancer cells and its depletion results in antitumour effects; thus, FASN has been defined as a promising therapeutic target." (PMID 38491348, 2024). "In ER+ cancer models, both genetic and pharmacological inhibition of FASN, hypersensitizes ERα to estrogen dependent transactivation, inducing estrogen receptor element (ERE) transcriptional activity and MAPK-ERK signaling." (PMID 37495653, 2023). "We also explored the effect of FASN inhibition on proliferation and mitochondrial respiration in these two cancer settings." (PMID 36650542, 2023). "It has been shown that the overexpression of lipid metabolism-related enzymes (e.g., FASN and SREBPs) is correlated with advanced stages of different type of cancers, poor patient survival, and cancer cell proliferation, invasion, and metastasis." (PMID 37190124, 2023). "Depletion of LDs in cancer cells induces apoptosis, prompting the emergence of small molecule antitumor drugs targeting LDs or key factors (e.g., FASN, SCD1) within the lipid synthesis pathway." (PMID 37474495, 2023). "Considering the important role of FASN inhibitors in cancer, researchers designed new protocols, such as nanoencapsulation, to improve their oral bioavailability and solubility." (PMID 37056351, 2023). "We did not provide direct in vivo experiment results to uncover the detailed mechanisms of CPT1A, SCD and FASN over-expression stimulating cancer cell proliferation and metastases." (PMID 38003694, 2023). "The activated fatty acid metabolism involved with FASN is related to cancer cell metastasis and low immune infiltration of MBC." (PMID 37696831, 2023). "FASN overexpression is related to poor cancer prognosis; therefore, FASN is considered to be a potential drug target for cancer therapy." (PMID 36674685, 2023). "In recent years, various drug candidates targeting lipid metabolism, which are likely relevant for cancer stem cells, have entered clinical investigation, including fatty acid synthase inhibitors." (PMID 37367867, 2023). "Only the lipogenic subtype shows good sensitivity to FASN inhibitors, indicating the plasticity of the metabolic network of cancer cells." (PMID 37056351, 2023). "FASN acts as an oncogenic factor due to its role in regulating fatty acid synthesis or inducing aberrant lipogenesis in cancer cells." (PMID 38060103, 2023). "Drug inhibition demonstrated that FASN overexpression is important for Cr(VI)-transformed cell survival and cancer properties." (PMID 38069382, 2023). "FASN up-regulation promotes cancer progression by enhancing lipid synthesis and signaling pathways, while its inhibition can impede tumor development and indicate poor prognosis." (PMID 38189049, 2023). "The activity of FASN in cancer cells has staid acquaintances with the regulation of antitumor immune response." (PMID 37256177, 2023). "FASN is the only human lipogenic enzyme that can be used for de novo fatty acid synthesis and is highly expressed in cancer cells." (PMID 36882446, 2023). "Cancer cells rely on fatty acid synthase (FASN)-mediated de novo lipogenesis, despite their access to environmental lipids." (PMID 37277821, 2023). "Our study indicates that the elevated level of FASN-mediated fatty acid metabolism is related to the cancer cell metastasis and low immune infiltration of MBC." (PMID 37696831, 2023). "Other studies have highlighted the significance of ACC and FASN expression in hormone resistance and cancer prevention." (PMID 38189049, 2023). "For example, fatty acid synthase (FASN), which is a multi-enzyme protein complex that catalyzes FA synthesis, is upregulated in cancer." (PMID 37190124, 2023). "In recent years, studies investigating antitumor strategies targeting metabolism regulation have increased, and FASN inhibition has shown promise in targeted cancer therapy." (PMID 36650542, 2023).
cancer (continued). "In T-cell malignancies, FASN-mediated FA synthesis provides essential lipid constituents to meet the demand for biological building blocks to sustain rapid cell division." (PMID 37256177, 2023). "Regarding lipid metabolism in non-cancer models, ginsenosides are known to suppress FASN and SREBP1." (PMID 38001865, 2023). "Given that FASN expression is upregulated in cancer cells and contributes to their proliferation and survival, FASN inhibition is also a potential therapeutic strategy for cancer." (PMID 37681411, 2023). "In another study, a proof‐of‐concept assay demonstrated that inhibitors of fatty acid synthase (FASN), which are key for cancer proliferation can be identified by MALDI‐MS." (PMID 36515561, 2023). "We found expression of Fatty Acid Synthase (FASN) was significantly increased in cancer cells when cultured using CMPOSTNhigh (p < 0.001)." (PMID 38049490, 2023). "In agreement with the postulated higher dependency of cancer cells from FASN, incubation with cerulenin was more toxic for HCT116 rather than for HCEC-1CT." (PMID 37117602, 2023). "At variance with normal cells, which derive their lipids from dietary intake or from lipid metabolism in the liver, cancer cells activate de novo lipogenesis, whose limiting enzyme is the fatty acid synthase (FASN)." (PMID 37561190, 2023). "Most cancer cells express high levels of FASN and SCD1 and have increased de novo fatty acid synthesis compared with normal cells." (PMID 37712874, 2023). "We found that these cancer-derived FBXW7β mutants lost their activity toward FASN degradation and in inhibiting lipogenesis, indicating that its intact activity is responsible for tumor suppression." (PMID 37202390, 2023). "Cancer cells that are positive for the oncogene HER2 were determined to overexpress the FASN enzyme, the key enzyme required for fatty acid biosynthesis." (PMID 37110218, 2023). "Overexpression of FASN is observed in multiple cancers and acts as a metabolic oncogene by modulating tumor growth and survival, making it a promising target for cancer therapy." (PMID 37078067, 2023). "Together, it is then critical to understand the role of FASN deregulation in cancer to find a better strategy for cancer treatment." (PMID 37202390, 2023). "In these cancer cells, the level of O-GlcNAc correlates with the expression level of FASN, which is a positive regulator of mTOR signaling." (PMID 37838167, 2023). "Another recent study showed that FASN overexpression ameliorates genotoxic insult induced cancer cell death by upregulating poly (ADP-ribose) polymerase 1 and DNA repair via NF-κB and SP120." (PMID 37270622, 2023). "Since the process is regulated mainly by FASN, the over-expression of FASN correlates with cancer proliferation, metastases, poor prognosis, and a higher risk of drug resistance." (PMID 38003694, 2023). "The first-generation of FASN inhibitors, such as Orlistat, C75, and cerulenin, were tested in preclinical studies in different types of cancers, such as mesothelioma, lung, breast, renal, and prostate cancers." (PMID 37760840, 2023). "The overexpression of the FASN enzyme promoted resistance in cancer cells that were treated with gemcitabine." (PMID 37110218, 2023). "In the reprogramming of lipid metabolism that occurs in cancer-associated fibroblasts (CAF), FASN is significantly increased in CAF, enhancing colorectal cancer cell migration." (PMID 38189049, 2023). "Actually, there is a strong interest in the development of FASN inhibitors for limiting cancer cell growth." (PMID 37120513, 2023). "It was reported that endogenously synthesized fatty acids are required for cancer cell proliferation, and the pharmacological inhibition of fatty acid synthase (FASN) has antitumor effects in cell lines, organoids, and xenograft models." (PMID 37685021, 2023). "The DNL enzyme fatty acid synthase (FASN) is overexpressed in many cancers and is pivotal for the increased production of fatty acids." (PMID 36934087, 2023).